MIR4705 (microRNA 4705)
Synonyms: hsa-mir-4705
Gene: MicroRNA gene on chromosome 13 (102,045,934 to 102,046,004, reverse strand). Ensembl gene ENSG00000264482.
Homologues: Orthologues: chimpanzee MIR4705 (100% identical).